LEP (leptin)
Diseases named in the same sentence as LEP in open-access papers (continued):
Sharing a sentence is not in itself a finding about the gene and the disease.
Insulin resistance (continued). "A logistic regression analysis was performed to investigate the effect of serum leptin, insulin resistance, treatment duration, and the genotypes of rs2167270 of the LEP gene on glycemic control status." (PMID 37241229, 2023). "Reductions in fat mass correlate with decreases in plasma leptin concentrations and insulin resistance." (PMID 38139229, 2023). "Leptin levels have also been shown to be increased in states of persistent hyperinsulinemia and insulin resistance." (PMID 38138907, 2023). "There is a significant correlation between OSAS and markers of metabolic syndrome (insulin resistance, dyslipidemia, and higher leptin levels), as well as a strong relationship between visceral adiposity and OSAS independent of BMI." (PMID 38004130, 2023). "In the literature, it has been claimed that the ADIPO/LEP ratio correlates with insulin resistance better than adiponectin or leptin alone." (PMID 37960185, 2023). "SOCS3, as a suppressor of cytokine signaling, is considered to promote insulin resistance by inhibiting insulin and leptin signaling during the inflammatory response." (PMID 36911682, 2023). "Both leptin and resistin are secreted proteins, and the levels of leptin and resistin increase when high-fat and high-sugar foods are ingested and in response to other factors, leading to insulin resistance." (PMID 36660274, 2023). "In particular, patients with PCOS had higher leptin levels compared to the controls, and an association between leptin levels and PCOS-related hyperandrogenism and insulin resistance was concluded." (PMID 37174950, 2023). "Many factors, such as insulin resistance, leptin, plasminogen activation inhibitor, adiponectin, adipokines, and other inflammatory cytokines, can be regulated by adipose tissue." (PMID 36830912, 2023). "Several studies documented that elevation in serum leptin level inhibited eating and accelerated metabolism when the percentage of body fat increased, and increases in secreted adiponectin also improved insulin resistance." (PMID 37993934, 2023). "Insulin resistance and increased leptin levels are early events in the development of NAFLD and NASH." (PMID 36674935, 2023). "The impaired synthesis of adipose tissue hormones such as leptin, adiponectin, visfatin, and tumor necrosis factor-α (TNF-α) is linked to the onset of atherosclerosis, type 2 diabetes, and insulin resistance." (PMID 37375800, 2023). "In the other hand, leptin levels reflect total body fat and insulin resistance that correlate positively with hepatic steatosis in diabetes subjects." (PMID 36790383, 2023). "Given that hepatic endotoxin is related to specific factors induced by leptin, leptin can affect insulin resistance." (PMID 37274349, 2023). "Fourth, obese people tend to consume high-calorie foods and high-fat diets, which have been shown to lead to hypothalamic mitochondrial dysfunction and endoplasmic reticulum contingencies, thereby promoting leptin and insulin resistance, which results in T2DM." (PMID 37810434, 2023). "In C57BL/6 mice fed a high‐fat diet (HFD), blueberry and mulberry juice prevented body weight growth, lowered blood cholesterol, reduced insulin resistance, attenuated lipid build‐up, and decreased leptin secretin." (PMID 38455221, 2023). "The plasma level of omentin positively correlates with the serum levels of adiponectin and high-density lipoproteins, but its plasma level negatively correlates with BMI, waist circumference, insulin resistance, triglyceride, and leptin levels." (PMID 37239168, 2023). "Previous study has demonstrated that the administration of leptin centrally can improve hepatic insulin resistance that is induced by a HFD." (PMID 37660067, 2023). "Not only is metformin effective at reducing insulin resistance and hyperglycaemia, but it also decreases circulating leptin and resistin, whilst leading to an increase in adiponectin." (PMID 36983885, 2023).
Insulin resistance (continued). "In contrast, leptin showed an opposite correlation pattern, reversing the trends noted with adiponectin in relation to insulin resistance, BMI, total testosterone, triglyceride, and LDL levels." (PMID 38155665, 2023). "At the same time, it can be deduced that the increase in FM will lead to a decrease in inhibition of appetite owing to the onset of leptin and insulin resistance." (PMID 37482777, 2023). "A recent study reported that leptin levels are elevated during pregnancy, which can exacerbate pregnancy-related insulin resistance and the onset of GDM, consistent with our findings." (PMID 37684563, 2023). "Serum glucose, triglyceride, leptin, insulin, and the insulin resistance index (HOMA-IR) were determined." (PMID 37242132, 2023). "In summary, both low serum leptin and high serum corticosterone levels contribute to the severe insulin resistance exhibited by these A-ZIP/F1 mice." (PMID 38260129, 2023). "The increasing plasma insulin and (log2)insulin:glucose ratio, higher leptin and low adiponectin are suggestive of insulin resistance in the feedlot finishing phase." (PMID 37041373, 2023). "Consistently, a significant effect of fat was observed in the leptin-to-adiponectin ratio, a marker of insulin resistance." (PMID 37061742, 2023). "The Leptin−/− pigs showed increased body fat and significant insulin resistance at the age of 12 months." (PMID 37705071, 2023). "Known for its appetite-suppressing and pro-inflammatory effects, leptin also influences insulin resistance depending on the abundance of leptin levels." (PMID 37299461, 2023). "The leptin-to-adiponectin ratio is elevated in MetS subjects and correlates positively with the insulin resistance index." (PMID 37629307, 2023). "Beyond leptin, excess adipose tissue mass also favors the production of other adipokines that promote insulin resistance and local inflammation." (PMID 37759429, 2023). "In these patients, leptin supplementation ameliorates insulin resistance, hyperglycemia, hypertriglyceridemia, hepatic steatosis, and female infertility." (PMID 37024989, 2023). "Insulin resistance, present in many patients with inappropriate lipid metabolism, leads to decreased levels of adiponectin, leptin, and other adipocytokines, and furthermore, results in liver free fatty acid intracellular transformation into triglycerides." (PMID 37762592, 2023). "Abdominal obesity makes a greater contribution to opposite profiles of leptin/ghrelin secretion leading to the onset of insulin resistance and abnormal blood pro-inflammatory cytokines values." (PMID 37668709, 2023). "A low plasma adiponectin/leptin (A/L) ratio has recently been suggested to be a marker of adiposopathy and a good predictor of insulin resistance." (PMID 36768493, 2023). "An increase in adiponectin plasma concentration decreases insulin resistance, while leptin leads to the development of insulin resistance." (PMID 36765298, 2023). "This increase in adiposity was paralleled by increased circulating leptin, which can improve insulin resistance and dysglycemia, which is possibly responsible for the observed improved glucose tolerance in the ZDSD rats after 15 weeks of OFS treatment." (PMID 37233701, 2023). "Patients with generalized lipodystrophy, who have low leptin levels and insulin resistance, respond well to leptin replacement, which normalizes LH and sex steroid levels." (PMID 37047811, 2023). "Visceral adipose tissue can increase basal fat breakdown, release free fatty acids (FFA), and specific cytokines secreted by visceral adipocytes, such as leptin and adiponectin, which can increase insulin resistance." (PMID 37674809, 2023). "Our interpretation is that when the amount of FM is high, then leptin/insulin resistance increases and the inhibitory effect declines." (PMID 37482777, 2023).
Insulin resistance (continued). "Alterations of adipokine ratios, specifically an excess of leptin and a paucity of adiponectin, promote insulin resistance and increased pro-inflammatory immune activity." (PMID 37759429, 2023). "There is a correlation between elevated leptin levels and decreased adiponectin levels with the development of insulin resistance and diabetes." (PMID 37724233, 2023). "We have also shown that the cord blood levels of C-peptide, leptin, and insulin resistance were higher in the T1DM group compared with the healthy controls." (PMID 36771307, 2023). "Leptin and resistin are inflammatory cytokines involved in the development of insulin resistance, whose levels increase with body fat mass." (PMID 37576981, 2023). "Diabetes can be efficiently treated with curcumin by increasing insulin resistance and decreasing leptin, resistin, and insulin levels." (PMID 37240220, 2023). "It is also notable that leptin levels were increased in TBT-group males since it is known that hyperinsulinemia and insulin resistance impair leptin signaling, leading to leptin resistance." (PMID 38077066, 2023). "Atypical antipsychotics appear to increase leptin levels, which impacts hunger cues and energy balance, and have been shown to result in insulin resistance." (PMID 38057934, 2023). "Elevated leptin levels and insulin resistance increased fatty acid β‐oxidation in aortic endothelial cells." (PMID 37596940, 2023). "Clinical workup revealed hyperandrogenism, insulin resistance, low leptin level (3.18 ng/ml), grade 1 hepatic steatosis and acquired partial lipodystrophy." (PMID 37248399, 2023). "In obese individuals with insulin resistance, high levels of leptin have been correlated with the amount of fat in the body, acting as a pro-inflammatory cytokine and amplifying the insulin resistance process." (PMID 36835413, 2023). "Improvement in psoriasis is usually accompanied by the remission of insulin resistance and a decrease in leptin levels." (PMID 36837593, 2023). "Secondly, low AGE consumption lowers leptin levels, with parallel increases in adiponectin concentration, which is consistent with previous studies highlighting the role of dAGEs in insulin resistance." (PMID 37446161, 2023). "Serum Leptin concentrations demonstrate an association with NAFLD which is mediated through insulin secretory dysfunction and insulin resistance in obese patients." (PMID 37705071, 2023). "Patients with SS have increased body fat, insulin resistance (IR), dyslipidemia, coagulation abnormalities, increased leptin, low-grade inflammation, endothelial dysfunction (ED), and non-alcoholic fatty liver disease (NAFLD)." (PMID 36742387, 2023). "For example, interleukin 6, leptin and tumour necrosis factor α take part in not only insulin resistance but also inflammation and other physiological processes." (PMID 37029402, 2023). "In conclusion, we identified two clusters of individuals differentiated by the degree of abnormalities in insulin resistance, leptin levels, and hippocampal hypoconnectivity." (PMID 35492025, 2022). "Increased circulating leptin was observed in insulin resistance and T2DM and correlated positively with lipids levels." (PMID 35241098, 2022). "Mice in the HFD group were accompanied by leptin and insulin resistance, which improved with dietary tannic acid intervention." (PMID 36359937, 2022). "The interaction between leptin and adiponectin, generally referred to as the leptin to adiponectin (L/A) ratio, has been reported to be significant in metabolic processes, suggesting plasma L/A ratio as a marker of insulin resistance." (PMID 35806240, 2022). "Lowering SOCS3 is the rationale for experimental drug therapies to override leptin and insulin resistance." (PMID 35406000, 2022). "Leptin related to homeostasis model assessment for insulin resistance (HOMA-IR) (r = 0.422, p = 0.006) was observed among type II subjects." (PMID 36295022, 2022).
Insulin resistance (continued). "Separately, dysfunctional insulin secretion and insulin resistance as well as elevated serum leptin levels have been reported in patients with NAFLD44." (PMID 36075960, 2022). "Adiponectin has potent effects on the glucose metabolism in the liver and improves glucose uptake, and leptin and adiponectin have an indirect and inverse correlation with insulin resistance." (PMID 35455483, 2022). "Accordingly, a significant positive correlation was found in obese subjects between leptin levels and body weight, body fat percentage, body mass index (BMI), and insulin resistance." (PMID 35628332, 2022). "With the recovery of mental illness and the improvement of metabolic indicators, the levels of leptin, insulin resistance and hs-CRP in the body decreased accordingly." (PMID 36090349, 2022). "In addition, an elevated leptin level may be a risk factor for insulin resistance." (PMID 35413791, 2022). "Individuals with high leptin levels should be monitored in this age group, and adequate healthcare should be provided to prevent chronic diseases related to insulin resistance." (PMID 36143007, 2022). "OB-participants showed significantly higher levels of leptin, insulin, Homeostatic-Model Assessment of Insulin Resistance (HOMA-IR), and TG." (PMID 36355134, 2022). "In keeping with findings in patients with other genetic disorders affecting the leptin-melanocortin pathway, SRC-1 variant carriers experience hyperphagia in childhood, but have a normal basal metabolic rate and mild insulin resistance." (PMID 35137184, 2022). "Further consistent with the relatively reduced accumulation of fat in individual adipocytes on HFD and adipose–derived insulin resistance, serum leptin and adiponectin levels were reduced in Ad-Tmem120a−/− mice on HFD compared to control littermates." (PMID 35027552, 2022). "We then compared urine oxalate excretion in ob/ob mice before and after leptin replacement or pioglitazone treatment, two maneuvers that reduce insulin resistance in ob/ob mice." (PMID 35851836, 2022). "Given this evidence, it is rational to propose that Fetuin B, a hepatokine involved in regulating insulin resistance and metabolism, is transcriptionally regulated by leptin released from adipose tissues." (PMID 35896788, 2022). "The combination of decreased leptin levels, and elevated ghrelin and cortisol levels, results in glucose intolerance and insulin resistance, which further aggravates the metabolic dysregulation." (PMID 35564491, 2022). "Although leptin and insulin resistance have been well characterized, catecholamine resistance remains largely unexplored." (PMID 34847077, 2022). "Our data demonstrate that cold stress induced a wide range of physiological changes, such as increased insulin resistance and IgA levels and decreased cortisol, T3, T4, leptin, adiponectin, GLP-1, and PYY levels." (PMID 35383199, 2022). "Central leptin and insulin resistance is commonly observed in the offspring of obese HFD-fed rat females." (PMID 35197931, 2022). "Agouti-related peptide-expressing neurons are also able to regulate systemic insulin resistance and they mediate the glucose-lowering action of leptin." (PMID 35742928, 2022). "Factors that contribute to pregnancy-induced insulin resistance include the secretion of adipokines (e.g., leptin) and cytokines (e.g., tumor necrosis factor-alpha, interleukin-6, and interleukin-1β), oxidative stress and, possibly, the gut microbiome." (PMID 33536549, 2022). "Chronic hypersecretion of insulin promotes both insulin resistance and hypersecretion of leptin from the adipose tissue." (PMID 36381191, 2022). "Conversely, high levels of Akkermansia are associated with a better metabolic status, in particular with higher leptin sensitivity, lower fasting blood glucose and insulin resistance, and lower adipocyte size." (PMID 36590404, 2022).
Insulin resistance (continued). "Similar to Nile rats, the risk of MetS in humans was increased in conjunction with increasing insulin resistance, elevated leptin, and decreased adiponectin, observations previously reported for Nile rats." (PMID 35893924, 2022). "The adiponectin/leptin ratio has been proposed to correlate better with insulin resistance and adipose tissue dysfunction than adiponectin or leptin alone." (PMID 36232660, 2022). "The adipocytokines, leptin, and adiponectin were related to insulin resistance-mediated cognitive dysfunction." (PMID 35682821, 2022). "In all three, there are very low levels of leptin, marked insulin resistance, hyperlipidemia, and fatty liver disease." (PMID 36241662, 2022). "Leptin showed considerable relationship with insulin resistance and this relationship remained after 8 weeks of CPAP therapy." (PMID 35755912, 2022). "In obese individuals, overproduction of adipocytokines in adipose tissue, such as leptin, induces insulin resistance, which subsequently activates the sympathetic nervous system and RAAS, and raises blood pressure." (PMID 35872884, 2022). "In the human liver, leptin has been shown to attenuate the number of insulin-induced actions that ultimately lead to insulin resistance." (PMID 36005598, 2022). "Genotyping of leptin and the leptin receptor gene can be used to predict insulin resistance and gestational diabetes during pregnancy." (PMID 36499312, 2022). "They attributed these changes to the insulin resistance observed in patients and the antagonistic effect between leptin and ghrelin in the hypothalamus." (PMID 35206438, 2022). "Increased leptin levels are also correlated with increased cat insulin resistance not only in obese but also in lean individuals." (PMID 36248900, 2022). "In the LPS + L and LPS + M groups, leptin and corticosterone levels and insulin resistance significantly reduced, whereas the LPS + H group exhibited slight effect on insulin resistance compared with the LPS group." (PMID 35428321, 2022). "Our findings also highlight the importance of hormonal pathways, notably those involving leptin and insulin resistance, as mediating mechanisms and potential targets for intervention in the treatment and prevention of common female reproductive conditions." (PMID 35104295, 2022). "More research is needed to better understand the roles that leptin plays in the development of the animal and the relationship between leptin, inflammation, and insulin resistance in animals." (PMID 35739885, 2022). "Key among these are leptin and adiponectin, which exert opposing effects on energy metabolism; leptin being related to insulin resistance, and adiponectin an insulin sensitizer." (PMID 36068284, 2022). "Relative to Cluster 2, Cluster 1 comprised individuals with higher leptin, a greater magnitude of insulin resistance, lower hippocampal cohesion and integration, but intact selective cognitive domains of interest." (PMID 35492025, 2022). "DM1 is a progeroid disease, characterized by age-related symptoms such as insulin resistance, impairments in leptin, and testosterone production." (PMID 35328504, 2022). "In multivariate linear regression analysis, serum leptin was correlated with BMI, homeostasis model assessment of insulin resistance (HOMA-IR), UA in women, and plus triglyceride (TG) in men." (PMID 35941672, 2022). "Leptin treatment prevented liver fat deposition and insulin resistance, induced greater insulin and leptin signaling capacity, decreased gene expression of orexigenic signals at the hypothalamic level, and induced browning in retroperitoneal adipose tissue." (PMID 35684076, 2022). "Leptin treatment is largely ineffective to improve insulin resistance and diabetic symptoms in these obese individuals." (PMID 36046814, 2022). "Gene expression and circulating leptin levels were reported to be increased by insulin; thus, the insulin resistance in PCOS patients is suggested to elevate leptin secretion from WAT." (PMID 36289764, 2022).